CD4 (CD4 molecule)
Diseases named in the same sentence as CD4 in open-access papers (continued):
Sharing a sentence is not in itself a finding about the gene and the disease.
COVID-19 (continued). "Single-cell RNA-seq analysis showed upregulation of caspase-1 in CD4+ T cells from COVID-19 hospitalized patients compared to unexposed controls." (PMID 40051620, 2025). "At 3 months post COVID-19, we have observed strong and persistent Omicron specific CD4+ memory T cells in hospitalised individuals in particular, and a significant proportion of CoV-TCRs targeting epitopes along the SARS-CoV-2 genome." (PMID 40242761, 2025). "Approximately 7–12% of moderate-to-severe COVID-19 survivors displayed persistent lymphopenia affecting B cells, CD4+ T cells, and Tregs at ~50 days post-symptom onset." (PMID 41141591, 2025). "A cohort study in Italy of PWH with low CD4 T cell count hospitalized with COVID-19 also found higher mortality and significantly longer hospitalization in this group compared to the general population." (PMID 40779550, 2025). "We found that age-related contraction of the naive lymphocyte pool and systemic inflammation were associated with suboptimal SARS-CoV-2–specific CD4+ and, even more evidently, CD8+ T cell immunity in patients with acute COVID-19." (PMID 39847442, 2025). "For example, PRDM1 (encoding BLIMP-1) in monocytes 40 and TCF family TFs (including TCF7) motifs in CD4 naive T cells are uniquely enriched in COVID-19 samples 40,41." (PMID 37425926, 2025). "Consistent with this, studies investigating severe influenza and COVID-19 have confirmed reduced counts of circulating MAIT as well as CD4+ and CD8+ T cells." (PMID 40766325, 2025). "Overall, this emphasizes the ongoing need to prioritize PWH for COVID-19 vaccines and medical interventions, especially those with low CD4+ cell counts and severe disease." (PMID 40811072, 2025). "According to the CIBERSORT algorithm, compared to normal samples, COVID-19 samples contain a higher proportion of neutrophils and activated dendritic cells, while the proportion of B cells, CD4, and CD8 T cells is relatively low." (PMID 40495223, 2025). "Meanwhile, compared with healthy controls at different stages, such as the acute phase, progressive phase, and convalescent phase, the proportion of Tregs in CD4+ T cells increased in COVID-19 patients, especially in the acute stage and progressive stages." (PMID 40114921, 2025). "Minimal peptide pools designed from the overlap of both methods featured improved performance to identify IEDB entries and induced robust CD4+ T cell activation in post-COVID-19 donors." (PMID 41291785, 2025). "Unlike healthy controls, who usually possess the majority of circulating PBMCs, participants with COVID-19 and influenza exhibited distinct inflammatory profiles characterized by declining B-cell counts and substantial decreases in CD4 and CD8 T cells." (PMID 40497938, 2025). "A lower CD4+ T cell count and higher HIV viral load were associated with a lower SARS-CoV-2 spike (trimer) total Ig titers in COVID-19-vaccinated PLWH." (PMID 40432125, 2025). "In PLWH, the immune response to primary mRNA COVID-19 vaccination is closely related to the quantity of CD4 T lymphocytes." (PMID 40299994, 2025). "PRF1+ CD4+ T cell subsets have been detected in settings such as chronic infections, malignancies, and COVID-19." (PMID 41328434, 2025). "Post hoc pairwise comparisons revealed statistically significant differences in inhibitor expression between Groups A and D for PD-1 on CD4+ cells and between the control group and COVID-19 groups for TIM-3." (PMID 40005306, 2025). "At admission to study (one month after the 3rd vaccine dose, ChAdOx1 nCoV-19/ChAdOx1 nCoV-19/BNT162b2 scheme, and 4 months before COVID-19 hospitalization), he had CD4+ T = 202 cells/mm3, CD8+ T = 79 cells/mm3, CD19+ = 6 cells/mm3." (PMID 40114918, 2025). "Another study showed that the pathogenicity of the COVID-19 cytokine storm was associated with increased numbers of Th 17 and highly proinflammatory CCR6+ CD4+ T cells in COVID-19 patients." (PMID 40236655, 2025).
COVID-19 (continued). "We observed lower blood values of CD4+ and CD8+ lymphocytes, while the CD4+/CD8+ ratio remained relatively similar in the group of patients with a proved severe clinical presentation of COVID-19." (PMID 40718799, 2025). "A similar study conducted in 2021 reported significantly lower SARS-CoV-2 anti-spike antibody titers among PLWH with CD4+ T cell counts of <500 cells, and, notably, <200 cells, following two-dose COVID-19 vaccination." (PMID 40432125, 2025). "In patients with severe COVID-19, leukopenia and lymphopenia, accompanied by a reduction in the percentages of CD4+ and CD8+ T cells, are common features." (PMID 41157669, 2025). "In general, patients with severe or critical COVID-19 exhibit a robust reduction in the absolute numbers of CD4+ and CD8+ T cells, respectively, compared to those with moderate disease." (PMID 41376637, 2025). "National COVID-19 vaccine guidelines recommending booster vaccines for all PWH should therefore specifically emphasise the need for booster vaccines in those with a CD4+ T-cell count < 200 cells per μL." (PMID 40388467, 2025). "We found that the percentage of Tregs to CD4+ T cells in COVID-19 patients was higher than that in healthy controls, especially in the AA, MP, MR, SA, and SP groups." (PMID 40114921, 2025). "SARS-CoV-2 spike (trimer) total Ig seropositive rates among PLWH who received two doses of a COVID-19 vaccine were 42.9% in those with CD4+ T cell counts < 200 cells/μL, 77.4% in those with ≥200–<500 cells/μL, and 86.0% in those with ≥500 cells/μL (p < 0.001)." (PMID 40432125, 2025). "With an available COVID-19 dataset, we show CD4+ T cell dysfunction in severe COVID-19 as TNF-α/TNF receptor 1-dependent immune pathways." (PMID 40429912, 2025). "Taken together, the results of our study demonstrate the potential benefits of an additional dose of mRNA-1273 to enhance protection in the SOTR population through the induction of CD4+ T-cell responses against COVID-19." (PMID 40248714, 2025). "On the contrary, compared to LTBI/COVID-19, COVID-19 has predominantly CD4+ T cells with high-polarized fractionated mitochondria (HFM) at baseline (p<0.01) and a similar profile is maintained even with stimulus." (PMID 40458413, 2025). "The model was validated using experimental data from middle-aged individuals with moderate COVID-19 progression, including measurements of viral load in the upper and lower airways, serum antibodies, CD4+ and CD8+ T cells, and interleukin-6 levels." (PMID 40431602, 2025). "Previous studies have reported that COVID-19 patients experience diminished cytotoxic responses, with CD4+ T cells acquiring a cytotoxic profile to compensate for CD8+ T cell dysfunction." (PMID 40458413, 2025). "COVID-19 seemingly can affect not only T cell differentiation within the thymus but also affect CD4+ T cell development in peripheral lymphoid organs." (PMID 41376646, 2025). "The proportions of CD8+ T cells, CD4+ memory resting T cells, activated NK cells, monocytes, M0 and M2 macrophages, and neutrophils were significantly different between COVID-19 and healthy samples (all p < 0.05)." (PMID 40149556, 2025). "In severe COVID-19, flow cytometry studies have shown reduced circulating lymphocytes, including CD3+, CD4+, and CD8+ T cells, with lower CD4+ counts linked to worse outcomes." (PMID 41462903, 2025). "This study investigates the epitope specificity, T cell receptor (TCR) usage, and phenotypic changes in SARS-CoV-2-specfic CD8+ and CD4+ T cells over time in convalescent individuals with COVID-19." (PMID 40092978, 2025). "The EPIC algorithm was validated, and under the standard of p < 0.05, the COVID-19 sample contained a high proportion of endothelial cells and macrophages, while the proportion of CD4 and CD8 T cells was relatively low." (PMID 40495223, 2025).
COVID-19 (continued). "A different picture was described for immune-compromised individuals, where mRNA COVID-19 vaccines resulted in much higher levels of IgG4 antibodies and impaired activation of CD4+ and CD8+ T cells." (PMID 41157248, 2025). "Specifically, we observed master TF motifs were enriched in COVID-19 monocytes and CD4 naive T cells." (PMID 37425926, 2025). "The COVID/PLWH group had lower CD4 counts (64 cells/mm3) and cytokine levels than other COVID-19 patients." (PMID 39861879, 2025). "The presence of SARS-CoV-2-specific CD4+ and CD8+ T cells is linked to reduced severity of COVID-19 during active infection." (PMID 40379979, 2025). "At the same time, COVID-19 vaccination has been reported to be just as effective in PLWH on ART with normal CD4+ T cell counts and a suppressed viral load, compared to uninfected controls." (PMID 40432125, 2025). "Regardless of the disease outcome, decreased frequency of CD28+, CD38+, and CD62L− CD4+ T-cell subsets were observed in both COVID-19 subgroups." (PMID 39597661, 2024). "Results of GO and KEGG analyses showed enrichment of mononuclear cell differentiation, regulation of T cell activation, defense response to the virus, and COVID-19 in CD4+ TEM cells with positivity for three markers." (PMID 39337460, 2024). "The frequency of CD4 T cell responders (SI > 2) was significantly reduced after JN.1 stimulation compared with the ancestral wild-type strain in the COVID-19-naïve group." (PMID 39772110, 2024). "At 6 months, S-specific CD4+ TCR clonal depth correlated with COVID-19 severity and long COVID symptoms, while CD8+ T-cell responses correlated with pre-existing lung disease." (PMID 39113913, 2024). "People with PCC showed skewed polarization of CD4+ Th subsets with altered functionality that was more similar to individuals with severe and critical presentations of acute COVID-19 than to people who fully recovered from mild disease." (PMID 39257580, 2024). "Results of GO and KEGG analyses showed that response to the virus, focal adhesion, cadherin binding, and COVID-19 were enriched in CD4+ TEM cells with two positive markers." (PMID 39337460, 2024). "Our prospective study showed that, both in the acute infection phase and convalescence, the CD4/CD8 ratio was in a state of marked inversion in severe COVID-19 patients." (PMID 39355257, 2024). "Specifically, CD4+ T lymphocytes serve as clear indicators of impaired immune function in patients with COVID-19 and hold predictive value for the disease’s severity, with their counts correlating with the seriousness of the illness." (PMID 38576608, 2024). "The CD4+Tcm cells were higher in the CONVIDECIA group (35.97 ± 9.651) than in the Recombinant COVID-19 Vaccine (Sf9 Cells) group (27.24 ± 7.461) and also higher than the KCONVAC vaccine group (24.08 ± 6.642) (P<0.1)." (PMID 39234239, 2024). "Among T cells, SARS-CoV-2-specific CD8+ and CD4+ T cells have been recently identified in the majority of COVID-19 convalescent patients and in vaccinated subjects." (PMID 39136010, 2024). "CD4+ TEM markers will be invaluable in ultimately understanding the common pathogenesis of PTB and COVID-19 and in developing more precise diagnostic and therapeutic molecular targets for clinical practice." (PMID 39337460, 2024). "In contrast, progression to severe COVID-19 was accompanied by stronger cellular immune responses, higher CD4 + T cell activation, and a higher number of in silico predicted high-affinity class I HLA alleles." (PMID 38902613, 2024). "COVID-19+ PLWH with a detectable VL (n = 18) had significantly lower percentages of CD4+ (p = 0.008), CD8+ EM4 CD57+ (p = 0.013), and CD8+ TEMRA pE1 T-cells expressing PD-1 (p = 0.005) than COVID+ PLWH with an undetectable VL (n = 19)." (PMID 39597537, 2024).
COVID-19 (continued). "For lymphocyte-related parameters, a lower level of lymphocyte count (HR = 0.571, 95% CI = 0.341-0.955, P = 0.033), and a higher CD4/CD8 ratio (HR = 2.473, 95% CI = 1.009-6.059, P = 0.048) were found related to the risk of severe COVID-19." (PMID 38454462, 2024). "The aim of our study was to evaluate the magnitude of immunological response to sequential BNT 162b2 mRNA vaccines in PLWH regarding demographic and clinical factors including CD4 status, viral load, COVID-19 morbidity, and hospitalization." (PMID 39772116, 2024). "For this, we directly stained PBMC from 63 COVID-19 patients for the complement subunits C3b and C1q and quantified the percentage of lymphocytes (CD4+, CD8+, or B cells) with complement deposition on their membranes." (PMID 38694513, 2024). "T lymphopenia, specifically of CD4+ T cells, is a common feature observed in human COVID-19 patients." (PMID 39066335, 2024). "In the multivariate analysis, several factors, including age, cancer, latest CD4 count, latest HIV viral load, and time since the last vaccination, remained significantly associated with COVID-19 hospitalization." (PMID 38630534, 2024). "Female sex, older age, cancer diagnosis and low CD4 count were associated with severe COVID-19 BTI, whereas previous COVID-19 was found to be protective against severe BTI." (PMID 39062187, 2024). "Nevertheless, they were also more engaged in preventive health measures such as having been vaccinated for COVID-19 and having higher CD4 counts." (PMID 38392862, 2024). "Overall, cytokine production by CD8+ T cells was limited, demonstrating that mRNA COVID-19 vaccines induce more robust CD4+ than CD8+ T-cell responses in pediatric populations." (PMID 38580714, 2024). "Studies on COVID-19 have shown that CD4+ T cells are vital for immuneresponses, activating B cells for antibodies, and aiding CD8+ T cells to eliminateSARS-CoV-2." (PMID 39536214, 2024). "After patients are infected with COVID-19, the virus attacks the lymphocyte immune system, resulting in decreased CD4+ and CD8+ T-cell counts." (PMID 39174035, 2024). "It is known that circulating SARS-CoV-2-specific CD8+ and CD4+ T cells in blood samples of COVID-19 patients exhibit immunodominant patterns for M, S, and N proteins." (PMID 38681561, 2024). "In this context, we recently reported that high frequencies of functional lung-resident memory CD4+ and CD8+ T cells contributed to protection against COVID-19-like symptoms and death caused by SARS-CoV-2 infection in a mouse model." (PMID 38605956, 2024). "This study based on sc-eQTL and MR analyses provides evidence for a causal effect of CD4+ TEM markers on PTB and COVID-19, separately." (PMID 39337460, 2024). "None of these studies provided information on the impact of HIV-related parameters (such as viral load, CD4+ T cell count, etc.)on hospitalization outcomes of COVID-19 patients." (PMID 38454994, 2024). "In patients with severe COVID-19, decreased frequencies of CD4+CD73+, CD4+CD25+CD39+ mTreg cells, and CD8+CD73+ were noticed if compared to both mild COVID-19 patients and controls." (PMID 39519310, 2024). "CD4+ T cell responses against the JN.1 subvariant were reduced compared with the ancestral strain in COVID-19-naïve individuals." (PMID 39772110, 2024). "Accordingly, PWH with normal CD4/CD8 ratio should be able to respond efficiently to vaccination against COVID-19." (PMID 38812512, 2024). "While no such genes were identified consistently across both study stages, GSEA on the stage 2 data revealed several B cell-related pathways and simulated CD4 T cell pathways that were exclusively enriched in ChAdOx1 nCoV-19 vaccinees at onset of COVID-19." (PMID 38649734, 2024). "Given the marked reduction in CD4+ T cell levels among elderly patients with severe COVID-19, we conducted a single-cell transcriptome analysis to elucidate the underlying molecular mechanisms related to these clinical characteristics." (PMID 39679195, 2024).
COVID-19 (continued). "Patients with severe COVID-19 often show reduced absolute lymphocyte counts, particularly CD4+ T- lymphocytes and CD8+ T-lymphocytes." (PMID 39691720, 2024). "The proportion and absolute count of total T cells and CD4+ T cells in COVID-19 group showed a significant decrease compared to HC group." (PMID 39113896, 2024). "In this study focusing on critically ill COVID-19 patients undergoing dexamethasone treatment, we examined mHLA-DR values and CD4 + T cell counts over time." (PMID 38762684, 2024). "It is known that mRNA vaccines against COVID-19 are capable of inducing robust CD4+ and CD8+ T cell responses and strong antibody responses." (PMID 38675761, 2024). "When analyzing all acute COVID-19 patients from whom we had both measurements (N = 62), we found an inverse correlation between the level of complement deposition on CD4 T cells and CD4 T cell numbers (R = −0.323, P = 0.0104)." (PMID 38694513, 2024). "Multiomic analysis of the COVID-19 vaccines on the CD4+ T cells provides valuable information on the DEGs occurring within the immune cells and allows us to predict which genes are poised for expression or are inaccessible for expression." (PMID 39340069, 2024). "In contrast, patients with severe COVID-19 exhibit broad lymphopenia and extensive functional impairment in CD4+ and CD8+ T cell subsets." (PMID 38811527, 2024). "Patients with mild COVID-19 exhibited reduced frequencies of CD4+CD25+CD39+ (activated/memory regulatory T cell [mTreg]) cells." (PMID 39519310, 2024). "Multiple doses of the mRNA COVID-19 vaccines also produce impaired activation of CD4 + and CD8 + T cells." (PMID 38280109, 2024). "Conversely, CD4+ T cells from post-COVID-19 patients with GBS showed high background proliferation in negative control cultures (no antigen)." (PMID 38233524, 2024). "Nearly 100% of people showed spike-specific CD4 T cell responses weeks after receiving two doses of the mRNA COVID-19 vaccine, and nearly 100% of people still showed memory CD4 T cell responses six months after the second dose." (PMID 39205152, 2024). "The frequency of responding IFN-γ-producing CD4+ T cells specific to individual epitopes was quantified, in each of the six groups of COVID-19 patients, using ELISpot assay (i.e., number of IFN-γ-spot forming CD4+ T cells or “SFCs”)." (PMID 38605956, 2024). "Published data indicate that COVID-19 vaccines can elicit robust CD4 T cell memory responses, and the mRNA-1273 vaccine generated spike-specific memory CD4 T cell frequencies that were greater in vaccinated individuals than in previously infected individuals." (PMID 39205152, 2024). "Compared to COVID-19, the children with MISC_C had lower CD4+GRB+/million CD3+ values (p-value: 0.02)." (PMID 39594853, 2024). "This contrast underscores the importance of CD8+ T cells in recovery and highlights CD4+ T cells’ potential role in chronic lung injury following severe COVID-19." (PMID 39768836, 2024). "Specifically, IFN-γ secretion and AIM SI by CD4+ T cells following BA.2.86 stimulation were reduced in these subjects compared with the COVID-19-naïve group." (PMID 39772110, 2024). "Compared with HIV-infected individuals with higher CD4+ T cell counts at baseline, PLWH with CD4+ T cell counts <200/μL were at increased risk of hospitalization and death from COVID-19." (PMID 38454994, 2024). "All COVID-19 patients displayed a lower proportion of T regulatory cells (CD4+CD25brightCD127low; Tregs) compared to HD, independently of the disease category (p<0.0001), and such difference decreased over time." (PMID 39136010, 2024). "In contrast, the Th2 cytokines IL-4 and IL-10 were moderately increased, suggesting the CD4 + T cell lineage is skewed towards Th2 in COVID-19." (PMID 38389037, 2024). "CD4+ T cell activation was negatively correlated with SARS-CoV-2 basal viral load in patients with severe COVID-19 (p = 0·043)." (PMID 38902613, 2024).